BRAF (B-Raf proto-oncogene, serine/threonine kinase)
Diseases named in the same sentence as BRAF in open-access papers (continued):
Sharing a sentence is not in itself a finding about the gene and the disease.
non-small cell lung carcinoma (353 papers, 2005 to 2026). A group of at least three distinct histological types of lung cancer, including non-small cell squamous cell carcinoma, adenocarcinoma, and large cell carcinoma. "Oncogenic BRAF mutations, including those in non-small cell lung cancer (NSCLC), are classified as Class I, II, or III." (PMID 41654519, 2026). "In non-small cell lung cancer, where BRAF mutations are found in 3% of cases, the combination therapy results in PFS of 9.0–14.6 months and an ORR of 63.2%–64%." (PMID 40896440, 2025). "The incidence of BRAF mutations in non-small-cell lung cancers (NSCLCs), particularly adenocarcinomas, has historically been underestimated due to the methods used for mutation detection." (PMID 40332392, 2025). "Oncogenic BRAF mutations affect 8% of solid malignancies and 4% of non-small cell lung cancer (NSCLC)." (PMID 41450930, 2025). "In non-small-cell lung cancer, acquired resistance to BRAF/MEK inhibitors often involves mutations in MEK1, PTEN, NRAS, and KRAS." (PMID 40332392, 2025). "Mutations in EGFR, KRAS, and BRAF are common in non-small cell lung cancer (NSCLC), while ALK, ROS1, and RET rearrangements define distinct molecular subtypes." (PMID 41012430, 2025). "BRAF mutations are found in 1–5% of non-small-cell lung cancer (NSCLC), with V600 and non-V600 accounting for approximately 50% each." (PMID 38538919, 2024). "The IDH1 and IDH2 mutations are also present in 0.9% of colorectal cancer, associated with the BRAF V600E mutation, in 0.5% of non-small cell lung carcinoma (NSCLC), co-existing with KRAS mutations and in melanoma, occurring with NRAS mutations." (PMID 39123479, 2024). "Non-small cell lung cancer samples with BRAF variants were less likely than expected to carry also alterations in EGFR and KRAS." (PMID 36275468, 2022). "Different from EGFR and ALK gene mutations, BRAF V600 mutation is relatively rare in non-small cell lung cancer, about 2–3% of which are adenocarcinoma." (PMID 36380085, 2022). "In 2017, dabrafenib and trametinib received FDA approval for the treatment of metastatic non-small cell lung cancer carrying the BRAF V600E mutation." (PMID 35912223, 2022). "With non-small cell lung cancer as example, the author further showed that the genetic interactions are BRAF mutation class-specific." (PMID 36275468, 2022). "BRAF gene mutations can be detected in approximately 2–4% of advanced non-small cell lung cancer (NSCLC) patients." (PMID 34436699, 2022). "The combination of dabrafenib and trametinib has also been approved for the treatment of non-small cell lung cancer with BRAF V600 mutations." (PMID 36275468, 2022). "For this analysis, only non-small cell lung cancer samples were used because this subgroup showed a balanced distribution of BRAF class 1, 2 and 3 mutations." (PMID 36275468, 2022). "Concomitant mutations in both KRAS and BRAF genes have been identified in non-small cell lung cancer (NSCLC)." (PMID 33402199, 2021). "The presence of BRAF mutations in non-small cell lung cancer (NSCLC) patients was first reported in 2011." (PMID 33260892, 2020). "Mutations of the BRAF oncogene are reported in tumors of patients with non-small-cell lung cancer in 2–4% of cases (about half of them are V600E mutation)." (PMID 33276639, 2020). "BRAF is reportedly mutated in 3–5% of non-small-cell lung cancer (NSCLC), 10% of colorectal cancers, 10–70% of thyroid cancers, and 52% of cutaneous melanomas." (PMID 32283865, 2020). "Categorization in a large cohort of BRAF-mutated non-small cell lung cancers based on the new classification system have showed less favorable outcome in patient with class-2 or class-3 BRAF mutations." (PMID 31277584, 2019). "BRAF mutations are found in ∼8% of human cancers and occur in 6–8% of non-small cell lung cancers (NSCLCs)." (PMID 28947956, 2017).
non-small cell lung carcinoma (continued). "For example, in non-small cell lung cancer, the efficacy of a BRAF mutant allele selective inhibitor is related to the BRAF V600E mutational status in the cancer cells." (PMID 26556852, 2015). "In a previous clinical trial of dasatinib, a tyrosine kinase inhibitor, for metastatic non-small cell lung cancer, a patient with BRAF p.Y472C mutation remained 4-year disease-free after treatment." (PMID 26498038, 2015). "BRAF mutations have been well described in non-small cell lung cancer (NSCLC) for several years, but the clinical features of patients harboring BRAF mutations are still not well described." (PMID 24979348, 2014). "Activating mutations in BRAF are found in 3% of non small-cell lung cancers, and mouse models have shown that expressing the mutant form of BRAF (BRAFV600E) in lung epithelium induce the formation of benign lung tumors." (PMID 23825589, 2013). "Although oncogenic KRAS mutations are frequent, BRAF mutations (BRAFV600E) are found in 3% of human non-small cell lung cancers." (PMID 23825589, 2013). "BRAF is mutated to lesser extent (2-3%) in non small cell lung cancers (NSCLC), and colo-rectal cancers (CRC) (8%)." (PMID 23006971, 2012). "Another gain that was associated with cluster B3 included BRAF, whose mutation has been reported in 3% of non-small cell lung cancer." (PMID 21151896, 2010). "BRAF V600E mutations occur in approximately 1%-2% of non-small cell lung cancers (NSCLCs)." (PMID 42256653, 2026). "However, there have been few reports of neoadjuvant treatment in patients with non-small cell lung cancer with rare mutations, such as BRAF (V-Raf murine sarcoma viral oncogene homolog B) V600E mutation." (PMID 41480531, 2025). "The optimal treatment sequence in non-small cell lung cancer harboring class I BRAF mutations and atypical BRAF variants remains unclear." (PMID 41152458, 2025). "In non-small cell lung cancer, class 1, 2 and 3 BRAF mutations were found in a similar frequency." (PMID 36275468, 2022). "A BRAF V600E mutation is found as driver oncogene in patients with non-small cell lung cancer." (PMID 32093631, 2020). "For example, alpelisib is currently in Phase III trials for treatment of PIK3CA driver mutations in cancers of the lung and other tissues, and a combination of dabrafenib and trametinib has clear efficacy in treatment of BRAF:V600E mutated non-small cell lung cancers." (PMID 31711466, 2019). "BRAF mutations have been found to be a driver mutation and maybe a therapy target in patients with non-small cell lung cancer." (PMID 22429583, 2012). "For instance, mutations in the epidermal growth factor receptor (EGFR) have been linked to resistance against tyrosine kinase inhibitors in non-small-cell lung cancer (NSCLC), whereas BRAF mutations have been shown to drive resistance in melanoma treatment." (PMID 41144441, 2025). "For instance, in copy number omics, we discover pathways corresponding to genes like EGFR, CDK6, RASSF5, BRAF, and CCND1, which are associated with non-small cell lung cancer." (PMID 40191608, 2025). "When used to treat BRAF600-mutant metastatic non-small cell lung cancer, dabrafenib, an inhibitor of BRAF, and trametinib, an inhibitor of MEK, had an objective response rate (ORR) of 64%." (PMID 40729346, 2025). "In patients with non-small cell lung cancer (NSLC) with EGFR mutations, Class II BRAF mutations are considered to play a major role in acquired resistance to EGFR inhibitors." (PMID 40977811, 2025). "In non-small cell lung cancer (NSCLC), molecular testing for EGFR mutations, ALK or ROS1 rearrangements, BRAF V600E mutations, and KRAS G12C mutations is now standard practice." (PMID 41010962, 2025). "The combination of BRAF inhibition with downstream MEK inhibition was first shown to be of clinical value in adults with non-small cell lung cancer (NSCLC) and anaplastic thyroid cancer." (PMID 40094009, 2025).
non-small cell lung carcinoma (continued). "In non-small cell lung cancer (NSCLC), common driver mutations involve EGFR, KRAS, ALK, and BRAF, which activate oncogenic signaling pathways such as PI3K/AKT and RAS/MAPK, promoting uncontrolled cellular proliferation." (PMID 40943394, 2025). "Although rare in non-small cell lung cancer (NSCLC), BRAF mutations present considerable therapeutic challenges." (PMID 39684685, 2024). "The incidence of BRAF mutations ranges from 1 to 5% in non-small-cell lung cancer (NSCLC), and is most common in lung adenocarcinomas, where BRAF V600E mutations account for more than 50% of all the BRAF mutation cases." (PMID 38538919, 2024). "This article presents a case of successful dabrafenib and trametinib combination therapy in a patient with BRAF V600E-mutant non-small-cell lung cancer who had a history of radiation pneumonitis and developed recurrence after conventional chemoradiotherapy." (PMID 38269311, 2024). "Class II alterations appear to be the predominant form of BRAF alteration in prostate, bladder, and non-small cell lung cancers." (PMID 39018217, 2024). "Currently, more than 200 different types of BRAF mutations have been identified in various types of cancer, particularly in melanoma, colorectal cancer (CRC), and non-small cell lung cancer (NSCLC)." (PMID 39456686, 2024). "The 11 currently reportable or actionable variants for non-small cell lung cancer (NSCLC) were extensively verified (n=126) (ALK, EGFR, BRAF, KRAS, NTRK 1/2/3, ROS, RET, MET, ERBB2)." (PMID 36522176, 2024). "Cervical cancer, hepatobiliary cancer, and non-small cell lung cancer harbor relatively high rates of Class III BRAF alterations." (PMID 39018217, 2024). "Accordingly, patients with a history of interstitial lung disease or pneumonitis were excluded from clinical trials of dabrafenib and trametinib combination therapy for patients with previously treated BRAF V600E-mutant metastatic non-small-cell lung cancer." (PMID 38269311, 2024). "V-Raf murine sarcoma viral oncogene homolog B (BRAF) alteration is one of the most essential driver genes of non-small cell lung cancer (NSCLC)." (PMID 38296628, 2024). "More recently, the combination of dabrafenib with trametinib has been approved for BRAF V600-positive advanced or metastatic non-small-cell lung cancer (NSCLC)." (PMID 36982163, 2023). "In this review, we discuss the molecular epidemiology of the main druggable genetic alterations in non-small cell lung cancer, namely EGFR, KRAS, BRAF, MET, and HER2 mutations or amplification, as well as ALK and ROS1 fusions." (PMID 33435440, 2021). "BRAF mutations are estimated to be present in 2-4% of non-small cell lung carcinoma (NSCLC) cases." (PMID 34466299, 2021). "Analysis of vesicles-associated nucleic acids for BRAF, KRAS, and EGFR mutations has shown higher sensitivity compared to plasma ctDNA in non-small cell lung cancer (NSCLC) patients." (PMID 34178690, 2021). "For example, measurement of Mitogen-Activated Protein Kinase (MAPK) pathway inhibition (via measurement of pERK) in non-small-cell lung cancer (NSCLC) patients receiving BRAF inhibitors can indicate direct drug-target interaction." (PMID 34737704, 2021). "Dabrafenib plus trametinib combination is approved in Europe for BRAF V600E-mutant metastatic non-small-cell lung cancer." (PMID 33276639, 2020). "For example, non-small cell lung cancer (NSCLC) regimens are organized by EGFR, ALK, BRAF, and ROS1 mutation status; kinase inhibitors are categorized by their target kinase(s) and biomarker-specific FDA labeling is noted." (PMID 32117976, 2020).
non-small cell lung carcinoma (continued). "The V599E and V600E mutations in v-raf murine sarcoma viral oncogene homolog B1 (BRAF) are observed in various carcinomas, while the L858R mutation in EGFR is observed in non-small cell lung cancer (NSCLC) cells." (PMID 31387297, 2019). "Recently, trametinib was approved for non-small cell lung carcinoma (NSCLC) harboring BRAF mutation, which implies that MEK inhibitors could be applied to other cancers with activation of the MAPK pathway." (PMID 29731968, 2018). "Here, we report our experience using next generation sequencing (NGS) to examine AKT1, BRAF, EGFR, ERBB2, KRAS, NRAS, and PIK3CA genes in 1006 non-small cell lung cancers in a clinical diagnostic setting." (PMID 29228562, 2017). "The principal mutations of EGFR, ALK, KRAS, BRAF, PIK3CA and HER2 were analyzed in 44 patients with non-small-cell lung cancer." (PMID 26968843, 2016). "This article reviews the current understanding of BRAF gene, its structure, expression, the signal pathway, as well as its relationship with cancer especially the targeted therapies for non-small cell lung cancer." (PMID 22429583, 2012). "Nevertheless, there is an argument suggesting that assessing the BRAF status could offer benefits in terms of managing and prognosing individuals with non-small cell lung cancer (NSCLC)." (PMID 38394545, 2024). "The effectiveness of combining immune checkpoint inhibitors (ICIs) with chemotherapy in treating non-small cell lung cancers (NSCLCs) with BRAF mutations has not been sufficiently explored." (PMID 38357200, 2024). "The re-sensitising effect that autophagy inhibitors have had on cancer cell lines and mouse models has been shown in a plethora of cancers, including, BRAF-mutant brain cancers and thyroid cancers, bladder cancer, non-small-cell lung cancer (NSCLC) and ALK-positive NSCLC." (PMID 37363731, 2023). "In advanced non-small cell lung cancer (NSCLC), V-Raf murine sarcoma viral oncogene homolog B1 (BRAF) mutation is highly malignant and has poor prognosis, and currently Dabrafenib in combination with Trametinib is approved for first-line treatment of patients with BRAF V600 mutation." (PMID 37989341, 2023). "Cases of proto-oncogene B-Raf (BRAF) V600E mutation are rare, accounting for 1%-4% of non-small cell lung cancers (NSCLCs), and its clinical features remain unclear." (PMID 35464513, 2022). "Recently, somatic mutations of EGFR and BRAF and gene rearrangements of ALK and ROS1 have been recommended for testing before the initial treatment of patients with advanced non-small cell lung cancer (NSCLC) based on the guidelines from major professional organizations." (PMID 34946321, 2021). "In non-small-cell lung cancer (NSCLC), BRAF G469R mutation showed a dramatic response to sorafenib, while other variant G469V could also affect sorafenib sensitivity in HCC." (PMID 32549224, 2020). "On a large group of patients with non-small-cell lung cancer, Mezequita investigated the relationship between the intensity of radon exposure and the occurrence of specific types of mutations such as EGFR, BRAF, KRAS and HER2, as well as ALK and ROS1 rearrangements." (PMID 33327615, 2020). "Estimates of BRAF aberration in non-small-cell lung carcinoma are less than 10%." (PMID 33042847, 2020). "In non-small-cell lung cancers, BRAF inhibitors are also shown to have a positive response." (PMID 31671773, 2019). "Approximately half of BRAF-mutated Non-small cell lung cancers (NSCLCs) harbor a non-V600 BRAF mutation, accounting for ∼40,000 annual deaths worldwide." (PMID 28947956, 2017). "Non-small-cell lung cancer (NSCLC) cell lines bearing EGFR, KRAS, BRAF, ALK or RET mutations were found with high level of PD-L1 expression, and this may be correlated with high levels of PI3K/AKT/mTOR pathway activation." (PMID 26919108, 2016).
non-small cell lung carcinoma (continued). "Initial implementation of this multiplexed SCODA mutation enrichment and detection assay focused on 46 mutations in 4 genes (BRAF, EGFR, KRAS, and PIK3CA), constituting a set of commonly encountered mutations of clinical relevance in colorectal and non-small cell lung cancers." (PMID 25575824, 2015). "Moreover, non-small cell lung cancers can test positive for ALK and BRAF mutations, which is useful for targeting the ALK and BRAF gene alterations during the course of molecular treatment." (PMID 25951941, 2015). "Although many molecular genetic studies indicate that there are some genetic mutations in non-small cell lung cancer (NSCLC), including EGFR, KRAS, PIK3CA, BRAF, ALK, DDR2, and PDGFRA, only a few studies have focused on the genetic events of salivary gland-type lung carcinomas." (PMID 26575266, 2015). "Moreover, a Phase Ib study suggests that multi-segment blockade of the RAS/RAF/ERK pathway may offer significant antitumor efficacy in patients with advanced and metastatic KRAS or BRAF-mutant non-small cell lung cancer." (PMID 40242250, 2025). "For example, the systemic treatment of advanced non-small cell lung cancer remained conventional chemotherapy for several decades until the emergence of TKI therapy following the discovery of several driver mutations including EGFR, ALK, ROS1, MET, RET, BRAF, and ERBB2/HER2." (PMID 39409947, 2024). "In addition to common EGFR activation mutations, targets such as ALK rearrangement, ROS1 rearrangement, RET rearrangement, BRAF V600E, MET exon 14 skip mutation, KRAS G12C, etc. have been gradually approved for targeted drug application in advanced non-small cell lung cancer." (PMID 38023198, 2023). "The aim of this study was to determine the frequency of EGFR, KRAS, BRAF, and HER-2 mutations in brain metastases from non-small cell lung carcinomas (BM-NSCLC)." (PMID 23930206, 2013). "Key gaps and needs in targeting KRAS/BRAF/MET and other genomic alterations in non-small-cell lung cancer." (PMID 39237103, 2025). "For non-small cell lung cancer (NSCLC) the current clinical guidelines recommend testing for genomic alterations in EGFR, BRAF, ROS1, ALK, KRAS, NTRKs, MET, RET, and ERBB2 genes." (PMID 38398180, 2024). "In contrast, YAP/TEAD binds to the enhancer region of PD-L1 in human non-small cell lung cancer (NSCLC), human malignant pleural mesothelioma, and BRAF inhibitor-resistant melanoma cells." (PMID 36294681, 2022). "Treatment planning for non-small cell lung cancer requires testing for EGFR, ALK, ROS1, BRAF, MET, RET and KRAS gene alterations." (PMID 34681592, 2021). "The National Comprehensive Cancer Network (NCCN) guidelines recommend “broad molecular profiling”, including BRAF, ERBB2 (HER2), MET, RET, NTRK, and ROS1, in addition to EGFR and ALK for metastatic non-small cell lung cancer (NSCLC)." (PMID 32375398, 2020). "Non-small cell lung carcinoma (NSCLC), the leading cause of cancer mortality worldwide, has known driver mutations of nodes on this pathway in ~75% of cases, including: ~30% KRAS, ~11% EGFR, ~7% BRAF and ~11% NF1 mutations." (PMID 31182717, 2019). "The utility of SL-BioDP is shown with a case study on the primary gene BRAF in cancer lung adenocarcinoma (LUAD), a form of non-small-cell lung cancer." (PMID 31671773, 2019). "On the other hand, in non-small cell lung cancer (NSCLC), a staggering ≈60% of the tumors had alterations in chief “driver oncogenes” including EGFR, BRAF, and KRAS combined." (PMID 31426419, 2019). "In recent years, series of driver genes, such as EGFR, KRAS/NRAS, BRAF, PIK3CA, ALK and ROS1 and so on, have been found in non-small cell lung cancer (NSCLC) one after another with the development of molecular detecting technology." (PMID 29526181, 2018). "Similar results are seen for other mutation-targeted agents including epidermal growth factor receptor (EGFR) inhibitors in non-small cell lung cancer (NSCLC), BRAF inhibitors in melanoma, and HER2 inhibition in breast cancer." (PMID 28056859, 2017).